NGF (nerve growth factor)
Diseases named in the same sentence as NGF in open-access papers (continued):
Sharing a sentence is not in itself a finding about the gene and the disease.
glaucoma (continued). "The RGC loss is associated with the downregulation of NGF and NGF receptor expression in the retina and ocular treatment with NGF significantly reduced the deficit induced by glaucoma." (PMID 25250333, 2014). "Another neurotrophic factor that has been investigated in glaucoma treatment is the nerve growth factor (NGF)." (PMID 24066234, 2013). "Examples of neuroprotective agents that have been investigated to restore neuronal degeneration in glaucoma include memantine, brimonidine, and neurotrophins such as ciliary neurotropic factor and nerve growth factor." (PMID 24066234, 2013). "NGF was assessed by ELISA immunoassay in undiluted aqueous samples collected from 32 consecutive patients undergoing surgery for cataract (control) or primary open angle glaucoma (POAG)." (PMID 18710547, 2008). "There is a great interest in investigating the levels of NGF in human aqueous in glaucomatous eyes, as suggested by animal studies, to gain a better understanding of the pathophysiology of glaucoma." (PMID 18710547, 2008). "With this new conceptual perspective, for corneal ulcer healing, this therapy perspective was now reviewed compared to standard existing eye therapies (i.e., anti-VEGF agents, corticosteroids, EGF, NGF, and others) used in corneal ulcer healing, therapy of neovascularization, and glaucoma therapy." (PMID 41471311, 2025). "Recombinant NGF has been licensed and is already used in clinical treatment of neurotrophic keratopathy; other promising clinical applications include treatment of glaucoma and retinitis pigmentosa." (PMID 40422222, 2025). "Ocular administration of NGF is currently approved for the treatment of neurotrophic keratopathy, but is has also been explored in some clinical trials for the treatment of ocular conditions such as glaucoma and retinitis pigmentosa." (PMID 40153582, 2024). "Glaucoma is one of the pathologies of the posterior eye segment in which NGF has found application." (PMID 39056738, 2024). "Ocular administration of NGF notably mitigated the impairments instigated by glaucoma." (PMID 38132117, 2023). "Indeed, several studies demonstrated that the NGF exerts prosurvival and regenerative effects in preclinical and clinical models of glaucoma, retinitis pigmentosa and AMD through the activation of different molecular pathways." (PMID 37111581, 2023). "However, the results showed strong trends towards significance in favor of NGF treatment groups and rendered the agent still relevant in treating glaucoma that warrants additional trials." (PMID 38276526, 2023). "Clinically, topical treatment with NGF for 3 months was shown to enhance optic nerve functions such as visual field, visual acuity, and contrast sensitivity in a small case series of patients with advanced glaucoma." (PMID 36579616, 2022). "Therefore, chronic NGF administration has been proposed to counteract both AD and glaucoma neurodegenerations." (PMID 34360760, 2021). "In the particular case of glaucoma, it has been shown, both in rat glaucoma models and in three patients with advanced glaucoma, that repeated topical administration of exogenous NGF prevented RGC apoptosis or, at least, resulted in a long-term improvement in their eyesight." (PMID 34360760, 2021). "It has been reported that the expression of two important neurological factors BDNF and NGF in glaucoma patients was significantly reduced compared to healthy individuals; such reductions can lead to poor cell function and impaired nervous growth and development." (PMID 34646884, 2021). "In addition, in patients with glaucoma, NGF eye drops resulted in an improvement of the INL function, neural conduction, visual field, optic nerve function, contrast sensitivity, and visual acuity." (PMID 32218163, 2020). "It would be interesting to explore the role of pro-NGF in glaucoma disease too." (PMID 28068360, 2017).
glaucoma (continued). "Similarly, NGF serum levels were stastistically reduced in the whole glaucoma population when compared to the healthy controls (4.1±1 pg/ml vs 5.5±1.2 pg/ml, p = 0.01)." (PMID 28068360, 2017). "Interestingly, we found similar serum levels of BDNF and NGF in advanced glaucoma patients and healthy controls." (PMID 28068360, 2017). "BDNF serum levels were not related to age, visual field mean deviation or retinal nerve fibre layer thickness either in glaucoma or in controls while NGF levels were significantly related to visual field mean deviation in the glaucoma group (r2 = 0.26, p = 0.004)." (PMID 28068360, 2017). "Therefore, further studies are required to confirm the therapeutic efficacy of NGF eye drops in glaucoma patients." (PMID 27657046, 2016). "Furthermore, administration of NGF eye drops restored TrkA levels in the retina, and protected RGCs from degeneration in experimental diabetic model and in glaucoma rat model suggesting that NGF treatment can restore NGF/proNGF balance during retinopathy." (PMID 26807305, 2015). "The application of NGF may open therapeutic perspectives for glaucoma and other neurodegenerative diseases." (PMID 25250333, 2014). "The data also indicate that NGF treatment may be an effective way to intervene in the process of glaucoma." (PMID 25250333, 2014). "After more research and deeper mechanistic understanding a randomized, controlled glaucoma, clinical trials need to be performed to evaluate the therapeutic effect of NGF in the treatment of glaucoma and this also will involve an evaluation of the magnitude and occurrence rate of adverse effects." (PMID 25250333, 2014). "In addition, these mouse lines provide a foundation for future efforts aimed at deciphering the role of NGF in the treatment of glaucoma." (PMID 25250333, 2014). "Thus, an enhanced understanding of the molecular pathways and mechanisms is required to better appreciate and potentially exploit the therapeutic potential NGF and its signaling pathways for the treatment of glaucoma." (PMID 25250333, 2014). "NGF plays an effect by preventing neuronal degeneration in animal models of neurodegenerative diseases, so the application of NGF as a neuroprotective strategy for the medical treatment of glaucoma should be reasonable." (PMID 25250333, 2014). "Positive results from the use of NGF in the treatment of classical neurodegenerative diseases lead researchers to investigate the role of NGF of the treatment of glaucoma based on glaucoma being a neurodegenerative disease related to the damage of optic nerves." (PMID 25250333, 2014). "NGF plays a crucial role during retinogenesis, influencing neuritic outgrowth, survival, and apoptosis, together with other neurotrophins and their related receptors, while in adulthood NGF is involved in several pathophysiological processes (homeostasis, ischemia, glaucoma, etc.)." (PMID 24627687, 2014). "However, in both glaucoma and control groups approximately 5.5% and 7.1% of samples had NGF values as high as 75.3 pg/ml and 17.9 pg/ml respectively." (PMID 18710547, 2008). "Several preclinical glaucoma models (e.g., induced ocular hypertension in rats) showed that topical or intraocular NGF administration did not cause further intraocular pressure elevation; instead, it promoted retinal ganglion cell survival, inhibited apoptosis, and supported functional recovery." (PMID 41471311, 2025). "Additionally, a phase II, randomized, double-blind, placebo-controlled trial (NCT02585540) is investigating the potential benefits of recombinant human nerve growth factor (rhNGF) in glaucoma patients, focusing on neuroprotective effects and visual field progression." (PMID 40683209, 2025). "The survival effects of NGF on retina have been investigated by several researchers, demonstrating that endogenous and exogenous NGF might be helpful in clinical approaches to treat retinal damage and attenuate RGC degeneration caused by glaucoma." (PMID 29636665, 2018).
glaucoma (continued). "BDNF and NGF serum levels are reduced in the early and moderate glaucoma stages, suggesting the possibility that both factors could be further investigated as potential circulating biomarkers for the early detection of glaucoma." (PMID 28068360, 2017). "Furthermore, ocular application of NGF in a rat model of high IOP reduced the progressive loss of RGCs, and excitingly, it resulted in a progressive improvement of the inner retinal layer function and neural conduction in patients with advanced glaucoma." (PMID 27657046, 2016). "Neurotrophic factors such as nerve growth factor (NGF), BDNF, CNTF, FGF-2, glial cell-line-derived neurotrophic factor (GDNF), neurturin (NRTN), and neuritin are particularly relevant to glaucoma." (PMID 39458902, 2024). "BDNF-mediated, CNTF-mediated, NGF-mediated, and GDNF-mediated neuroprotection in glaucoma has great potential, but retinal delivery is challenging, and adverse effects must be addressed." (PMID 38132117, 2023). "Both BDNF and NGF are known promoters of RGC survival upon glaucomatous injury and their application as potential neuroprotective drugs in glaucoma management is well-studied." (PMID 35681479, 2022). "Ephrin, NGF, and ERBB2 as three important pathways identified by their high expression are shared by glaucoma and miR-204 target genes." (PMID 34646884, 2021). "This study explored levels of NGF and BDNF in serum of glaucoma patients with different stages of the disease in comparison with healthy controls." (PMID 28068360, 2017). "In our study, women had higher serum levels of NGF and BDNF compared to men, both in glaucoma patients and in healthy controls and this finding was already reported in previous studies." (PMID 28068360, 2017). "Although NGF treatment is effective in the treatment of glaucoma, in some studies, there are also some negative reports; one example is the proapoptotic effect of p75 neurotrophin receptor (p75NTR) in glia cells; binding of NGF to p75NTR is associated with retinal ganglion cell apoptosis." (PMID 25250333, 2014). "Ongoing research shows that glaucoma increases the basal level of TrkA in the LGN and NGF administration further enhances this increase." (PMID 25250333, 2014). "Thus, neurotrophic supplementation therapies, such as nerve growth factor (NGF), brain-derived neurotrophic factor (BDNF), or ciliary neurotrophic factor (CNTF), have been studied for preventing the progression of glaucoma." (PMID 39408817, 2024). "In glaucoma patients, NGF was safe and well tolerated, but produced no statistically significant results in the phase Ib clinical trial." (PMID 38276526, 2023). "Subgroups analysis showed that serum levels of NGF were significantly lower in early (3.5±0.9 pg/mL, p = 0.0008) and moderate glaucoma (3.8±0.7 pg/ml, p<0.0001) but not in advanced glaucoma (5.0±0.7 pg/ml, p = 0.32) compared to healthy controls." (PMID 28068360, 2017). "In conclusion, according to the results of our study serum levels of NGF and BDNF vary across different stages of glaucoma, suggesting that their levels might be the expression of progressive neurodegenerative damage that occurs over the course of the disease." (PMID 28068360, 2017). "The finding of higher serum levels of both NGF and BDNF in patients with advanced stage of the disease when compared to patients with early and moderate glaucoma, and similar to the levels found in healthy control subjects is matter of speculation." (PMID 28068360, 2017). "Most recently, a phase 1b clinical trial evaluating the safety and efficacy profiles of recombinant human NGF eyedrops in glaucoma patients for 8 weeks revealed neither major adverse events nor statistically significant short-term neuroenhancement in terms of structural and functional measures." (PMID 36579616, 2022). "A current hypothesis is NGF and BDNF are involved in the pathogenesis of RGCs death in glaucoma." (PMID 28068360, 2017).
glaucoma (continued). "Both BDNF and NGF were not even related to the morphological glaucoma parameter (RNFL)." (PMID 28068360, 2017). "As well, NGF serum levels were significantly lower in early (3.5±0.9 pg/ml, p = 0.0008) and moderate glaucoma groups (3.8±0.7 pg/ml, p<0.0001) but not in the group of advanced glaucoma (5.0±0.7 pg/ml, p = 0.32) when compared to healthy controls." (PMID 28068360, 2017). "Taken together, these in vitro and previous in vitro/in vivo studies on NGF administration support the hypothesis that the purified NGF molecule represent a critical survival factor not only for RGC degeneration, as observed in Glaucoma and Maculopathy, but also for photoreceptor degeneration." (PMID 25897972, 2015). "Both BDNF and NGF serum levels were not statistically related to RNFL thickness in the whole glaucoma sample (BDNF/RNFL r2 = 0.0002, p = 0.9; NGF/RNFL r2 = 0.01, p = 0.48) and RNFL thickness was not statistically related to age (r2 = 0.01, p = 0.44)." (PMID 28068360, 2017). "BDNF and NGF serum concentrations were not related to age in the whole glaucoma population (BDNF/age r2 = 0.004, p = 0.65; NGF/age r2 = 0.10, p = 0.08) nor in controls (BDNF/age r2 = 0.03, p = 0.52; NGF/age r2 = 0.02, p = 0.67)." (PMID 28068360, 2017). "In the whole glaucoma population, BDNF serum levels were not statistically related to MD values (r2 = 0.08, p = 0.06), while NGF serum levels were statistically related to MD values (r2 = 0.26, p = 0.004)." (PMID 28068360, 2017). "Nevertheless since NGF and BDNF may be produced also by a variety of non-neural cell types in response to different stimuli, further investigations are required to assess their role as potential biomarkers of glaucoma." (PMID 28068360, 2017).
asthma (49 papers, 2005 to 2024). "NGF-induced neurokinin causes neurogenic airway inflammation, alters neuroplasticity, and leads to a variety of pathophysiological changes in asthma." (PMID 38049878, 2023). "The results of the present study further the understanding of the mechanisms underlying NGF augmenting the Th2 response in asthma." (PMID 25289030, 2014). "Previous animal studies have shown that overexpression of NGF in Clara cells is associated with increased AHR in an allergen sensitization model of asthma." (PMID 25296021, 2014). "Our results present evidence that asthma during the pregnancy of rat dams promotes asthma susceptibility in their offspring, and that the transformation of AMCCs to neurons induced by NGF plays an important role in this process." (PMID 23137120, 2012). "We showed that maternal asthma during pregnancy promoted susceptibility to asthma in rat pups, and that the transformation of AMCCs to neurons induced by NGF exposure in utero played an important role in this process." (PMID 23137120, 2012). "It has also been reported that NGF is associated with a variety of autoimmune and inflammatory diseases (e.g. allergic diseases and asthma, and intestinal mucosa inflammation) in which elevated NGF levels correlate well with the severity of the diseases." (PMID 21385399, 2011). "In this review, we summarize the functions of NGF as well as some potential underlying mechanisms in pulmonary fibrosis (PF), coronavirus disease 2019 (COVID-19), pulmonary hypertension (PH), asthma, chronic obstructive pulmonary disease (COPD), and lung cancer." (PMID 34502019, 2021). "Evolving evidence suggests that nicotine may contribute to impaired asthma control by stimulating expression of nerve growth factor (NGF), a neurotrophin associated with airway remodeling and airway hyperresponsiveness." (PMID 33082140, 2020). "In addition to its classic role in nervous system physiology, NGF is considered as an important factor associated with the pathogenesis of allergic diseases, particularly asthma, by regulating of mast cell differentiation." (PMID 30939862, 2019). "Despite the fact that NGF is known primarily for its classical role in the physiology and pathology of the nervous system it level is considered as an important factor associated with the pathogenesis of allergic diseases, in particular asthma." (PMID 30939862, 2019). "In addition to its classic role in the pathophysiology of the nervous system, NGF is considered to be an important factor associated with the pathogenesis of allergic diseases, particularly asthma, due to its influence on the differentiation of mast cells." (PMID 30939862, 2019). "We found recently that hyperinnervation of the adrenal medulla in asthmatic rats may contribute to the greater expression of NGF; the change of the adrenal medulla led to functional changes, which was associated with the transformation of AMCCs in asthma." (PMID 23137120, 2012). "Hence, NGF may play a role in the early airway response (EAR) in asthma, since anti-NGF attenuated the early allergen-induced bronchoconstriction, and NGF causes histamine release from mast cells and basophils." (PMID 16441896, 2006). "The results showed that Nrf2/HO-1’s expression decreased and NGF’s expression increased in the Asthma group, while vitamin D administration restored the gene expression levels." (PMID 38273268, 2024). "NGF exacerbates airway inflammation in asthma by promoting smooth muscle cell proliferation and inducing the Th2 immune response." (PMID 38273268, 2024). "NGF can also induce the proliferation of bronchial smooth muscle cells and aggravate the airway remodeling of asthma." (PMID 38049878, 2023). "NGF is a dual regulatory mediator of neuroplasticity and immune regulation and has obvious effects on airway remodeling and airway inflammation in asthma." (PMID 38049878, 2023).